ABCG1 (ATP binding cassette subfamily G member 1)
Diseases named in the same sentence as ABCG1 in open-access papers (continued):
Sharing a sentence is not in itself a finding about the gene and the disease.
tumor (82 papers, 2012 to 2026). "ABCG1-associated differentially expressed genes are implicated in various critical pathways governing tumor progression, suggesting a role for ABCG1 in ccRCC progression through its modulation of key proliferation and apoptosis-related gene expressions." (PMID 40520894, 2025). "The purpose of this review is to provide an in‐depth review of the tumor‐associated aspect of ABCG1 in tumor progression." (PMID 38896016, 2024). "Macrophages in Abcg1 knockout mice have a predisposition to M1 polarization, which is characterized by increased NF-κB activation and direct cytotoxicity toward tumor cells in vitro." (PMID 39857239, 2024). "Further research revealed that the loss of ABCG1 inhibited tumour growth by regulating the survival and phenotype acquisition of macrophages in tumours." (PMID 37261073, 2023). "Then, researchers adopted a bone marrow chimaera and found that ABCG1 deficiency changed the balance between tumour-promoting immune cells and antitumour immune cells in the TME." (PMID 37261073, 2023). "ABCG1, for example, is known to efflux cholesterol, and expression of both ABCA1 and ABCG1 are needed to deplete lipid rafts in tumour-associated macrophages." (PMID 35454786, 2022). "In PC9 and A549, the deficiency of ABCG1 was reported to inhibit tumor growth by transforming macrophages from a tumor‐promoting phenotype into a tumor‐fighting phenotype." (PMID 33939316, 2021). "Conversely, ABCG1 deletion is associated with an anti-tumoral M1 phenotype, increased NF-κB activation and inhibition of tumor growth in high-cholesterol diet-fed mice." (PMID 32823961, 2020). "It was shown that myeloid specific deficiency of Abcg1 or Abca1 was associated with decreased tumor growth, increased polarization of TAMs towards M1 phenotype, and decreased numbers of specific MDSCs subsets in the tumors." (PMID 31374929, 2019). "Further studies are needed to discover the underlying mechanism of Apo A1-ABCA1/ABCG1-HDL axis on tumor progression." (PMID 31598156, 2019). "The recently observed anti-tumor phenotype with Abcg1 deficiency was also noted to be accompanied by enhanced Abca1 expression in TAMs, though the potential role of ABCA1 was not examined." (PMID 29069761, 2017). "In prior studies, the anti-neoplastic activity of apoA-I and HDL, and the tumor protection observed with Abcg1 deficiency, were suggested to be mediated in part by the myeloid immune cell subset." (PMID 29069761, 2017). "Figuring out the detailed role and the underlying mechanisms of ABCG1 within tumors may provide a promising target for precise therapy especially for ABCG1‐overexpression tumor patients." (PMID 38896016, 2024). "In contrast, loss of the ABCG1 pump could trigger the accumulation of redundant harmful lipids, leading to tumor cell death." (PMID 36671802, 2023). "Generally, ABCG1 deficiency in vivo inhibited tumour growth and increased animal survival." (PMID 37261073, 2023). "Deficiency in either ABCA1 or ABCG1 in macrophages attenuates tumor growth in xenograft models." (PMID 30283400, 2018). "Our study also touches upon an ABCG1-mediated mechanism underlying tumor progression." (PMID 30364132, 2018). "Not only cancer cells but also tumor-associated macrophages can express ABCG1 that pump cholesterol out, implicating that ABCG1 in tumor milieu may also play a detoxifying role." (PMID 30364132, 2018). "Thus, the role of ABCG1 as a potential diagnostic and therapeutic target in cancer is of clinical interest and requires new studies to better understand the putative links of transporter function to tumor development and progression." (PMID 39857239, 2024). "In vitro experiments further elucidated that ABCG1 knockout notably inhibited proliferation, migration, and invasion of tumor cells while concurrently increasing apoptosis levels." (PMID 40520894, 2025).
tumor (continued). "The deletion of genes encoding ATP‐binding cassette (ABC) transporter proteins, which mediate cholesterol efflux (such as ABCA1 and ABCG1), has been shown to reverse the tumor‐promoting functions of TAMs and slow tumor progression." (PMID 41020041, 2025). "The transcriptional expression of ABCG1 across 33 different tumor types and adjacent tissues (n = 10,534) was assessed via RNA sequencing data extracted from the TCGA database." (PMID 40520894, 2025). "The six‐gene diagnostic model (AIFM2, ABCG1, LIPG, DGAT2, LPCAT1, and VCP) demonstrated near‐perfect classification of tumor versus normal tissues (AUC ≈0.99 in ROC analysis; 99.8% accuracy in SVM analysis)." (PMID 40804485, 2025). "Concurrently, ABCG1‐mediated cholesterol efflux promotes M2 polarization: tumor cells export cholesterol via ABCA1/ABCG1 transporters." (PMID 40904700, 2025). "Cholesterol metabolism further bridges amino acid signaling: ABCG1‐driven cholesterol efflux from TAMs disrupts lipid rafts on tumor cells, amplifying mTORC1 sensitivity to extracellular leucine and activating pro‐growth ribosomal biogenesis." (PMID 40904700, 2025). "ABCA1 and ABCG1 regulate cholesterol efflux and influence immune responses: ABCA1 deficiency impairs T cell receptor signalling, while ABCG1 loss promotes an anti-tumor M1 macrophage phenotype." (PMID 41432903, 2025). "Immunohistochemistry revealed a strong expression of FABP3 in tumor cells, located in proximity to ABCG1+ cells." (PMID 40661379, 2025). "Collectively, these investigations suggest a potential oncogenic role for ABCG1, yet the mechanisms underpinning its involvement in carcinogenesis and tumor progression warrant additional exploration." (PMID 40520894, 2025). "Cholesterol efflux transporter proteins ABCA1 and ABCG1 in macrophages 33, and the cytokines secreted by tumor cells including CTSK34, IL-10 and CSF135, have been shown to trigger the polarization of TAMs towards the M2 phenotype." (PMID 38993570, 2024). "Relevant molecules that regulate the expression of ABCG1 in multiple cancers and subsequent effects on tumor progression." (PMID 38896016, 2024). "In the ω-3 group, GPR120 WT BMD M2-like macrophages infiltrating the tumor were significantly reduced in number and gene expression of cholesterol transporters Abca1, Abca6, and Abcg1." (PMID 37872251, 2024). "Apart from tumor cells, ABCG1 also functions actively in tumor microenvironment to influence tumor initiation and progression." (PMID 38896016, 2024). "In conclusion, ABCG1 plays a vital role in promoting cancer cell growth and tumor progression through lipids efflux via EVs." (PMID 38896016, 2024). "In tumor microenvironment, ABCG1 plays a substantial role in immunity response through macrophages to create a tumor‐favoring circumstance." (PMID 38896016, 2024). "On the other hand, in a previous work, we had shown that tumor ABCG1 was related to the disease severity with a lower expression in the highest SBR-grade tumor (pejorative situation)." (PMID 39519412, 2024). "ABCG1 enhances tumor‐promoting ability through conferring stem‐like properties to cancer cells and mediates chemoresistance in multiple cancers." (PMID 38896016, 2024). "ABCG1 is indicated to confer tumor stemness through activating the H19/HIF‐1α/PDK1 signaling pathway to induce rapid cancer cell growth and adaption to the condition of hypoxia and insufficient energy supply." (PMID 38896016, 2024). "The balance between tumor‐promoting and tumor‐fighting immune cells within the TME is broken by aberrant expression of ABCG1, leading to a tumor‐favorable environment." (PMID 38896016, 2024). "ABCG1 promotes cholesterol efflux from tumor cells, thereby regulating intracellular cholesterol homeostasis, which is also a vital mediator of LXRs effects." (PMID 39308527, 2024).
tumor (continued). "Consistent with a tumor‐promoting role, ABCG1 enhances cell stemness properties and confers CSCs a survival advantage to induce tumor formation, metastasis, relapse, and resistance toward treatment in multiple cancers." (PMID 38896016, 2024). "Knocking out the ABCG1 gene responsible for this transport pathway in mice resulted in excellent anti-tumor characteristics." (PMID 39381047, 2024). "In tumor progression, the expression of ABCG1 interacts with non‐coding RNA and some other signal molecules." (PMID 38896016, 2024). "ABCG1 can also confer stemness to tumor cells, improving the survival advantage of cancer stem cells." (PMID 38896016, 2024). "Nevertheless, some research found that ABCA1/ABCG1 had a distinct involvement in the polarization of macrophages during tumor progression." (PMID 38540127, 2024). "A comprehensive searching about ABCG1 and tumor was conducted up to November 2023 using proper keywords through databases including PubMed and Web of Science." (PMID 38896016, 2024). "The PRDM family members play role in cancer suppression, while ABCG1, BACE2, and TFF1 are implicated in tumor formation in various studies." (PMID 38395755, 2024). "We also demonstrated fasting to upregulate the cholesterol trasporter ABCG1 in tumours and to also downregulate ACAT1 in the HCT116 xenografts." (PMID 37907500, 2023). "The study found that Abcg1−/− mice bearing MB49 tumours survived longer than WT mice bearing MB49 tumours." (PMID 37261073, 2023). "Genetic deletion of ABCG1 reverses the tumor-promoting functions of TAMs and leads to a reduction in tumor burden." (PMID 38060103, 2023). "ABCG1 is a cholesterol lipid efflux pump that plays a well-known role in tumor growth, conferring chemoresistance to various malignant tumors 11 and presenting a major obstacle for effective clinical cancer treatment." (PMID 34539880, 2021). "This means that the upregulation of ABCG1 leads to an increase in M2 macrophages, which is conducive to tumor growth." (PMID 33825659, 2021). "The genetic deletion of ABCA1 and/or ABCG1 revert the tumor-promoting functions of TAMs and reduces tumor growth." (PMID 33391518, 2021). "We examined tumor tissues from subcutaneous xenografts by immunohistochemistry and also observed a decreased proportion of ABCG1 in IP6 treatment group (10.67 ± 6.43 vs. 26.12 ± 5.29, p = 0.0332)." (PMID 34539880, 2021). "ABCG1 is a cholesterol lipid efflux pump that plays a well-known role in tumor growth, conferring chemoresistance to various malignant tumors." (PMID 31931755, 2020). "Among Gli1 regulated ABC transporters, ABCG1 was expressed at significantly higher levels in cancer tissues respect to non-tumour tissues and in CD133+ cancer cells respect to CAFs." (PMID 32814794, 2020). "The positivity rate of HIF-1α as well as ABCG1 around necrotic areas were significantly reduced in the ABCG1-depleted tumor compared with the control tumor." (PMID 30364132, 2018). "We are currently investigating further mechanisms underlying ABCG1-mediated HIF1 activation and tumor growth." (PMID 30364132, 2018). "On the contrary, we showed that ABCG1 protein expression was markedly upregulated in tumour cell lines, especially in the AR-null one; the mechanisms and the consequences of ABCG1 upregulation on the metabolism of PCa cells deserve further investigations." (PMID 29396407, 2018). "Most recently, apoA-I and myeloid ABCG1 have been shown to influence the anti-tumor function of immune cells." (PMID 29069761, 2017). "The observation that animals with myeloid deficiency of ABCA1 (A1−M/−M) and or ABCG1 (G1−M/−M) transporters had smaller B16F10 tumors and reduced accumulation of tumor-infiltrating MDSCs is, at present, only associative." (PMID 29069761, 2017). "ATP-binding cassette transporter G1 (ABCG1) inhibited BCa growth through a phenotypic shift from a tumor-promoting M2 to a tumor-fighting M1." (PMID 29190997, 2017).
tumor (continued). "In contrast, myeloid ablation of ABCG1 resulted in a statistically significant decrease (2.7-fold) in numbers of monocytic MDSCs, Ly-6GnegLy-6CHi (median=0.9 and 0.33 × 106 cells/gram tumor tissue in WT and G1−M/−M, respectively, p<0.01, lower plot)." (PMID 29069761, 2017). "Changes in cholesterol metabolism or levels of components of cholesterol homeostasis namely apoA-I/HDL, ABCA1, ABCG1, and SR-B1 are known to affect immune responses which in turn impact anti-tumor effects." (PMID 26617517, 2015). "The study found that Abcg1-/- macrophages exhibited an intrinsic bias towards M1 polarization, characterized by increased NF-κB activation and enhanced direct cytotoxicity against tumor cells in vitro." (PMID 40520894, 2025). "This discrepancy suggests that the role of ABCG1 in cancer may vary depending on the tumor type and cellular environment." (PMID 40508156, 2025). "Following intervention with the cholesterol inhibitor MβCD, the expression of cholesterol synthesis-related proteins (CD36, SREBP2 and HMGCR) decreased, while the expression of cholesterol efflux-related proteins (APOA1 and ABCG1) increased, leading to significant inhibition of tumor cell growth." (PMID 41041664, 2025). "Furthermore, ABCG1 can modulate the tumor microenvironment by regulating macrophage activity, thereby promoting tumor growth." (PMID 40520894, 2025). "Animal studies have shown that blocking ABCG1 restores anti‐tumor TAM function." (PMID 40904700, 2025). "However, heightened nuclear ABCG1 expression correlates with poor prognosis, suggesting a critical role for the subcellular distribution of ABCG1 in tumor recurrence." (PMID 40520894, 2025). "One of the reasons may rely on the altered cholesterol levels in tumor cells, since ABCG1 plays a pivotal role in sterol transporting." (PMID 38896016, 2024). "ABCG1 plays a critical role in promoting tumor development mainly through four aspects including tumor initiation and progression, chemoresistance, cancer cell stemness and tumor microenvironment." (PMID 38896016, 2024). "The detailed role and function of ABCG1 in tumor progression." (PMID 38896016, 2024). "In addition to tumor cells, ABCG1 is identified to interact with cells in the tumor microenvironment." (PMID 38896016, 2024). "Numerous reports indicate that ABCG1 promotes cancer cell stemness and tumor growth." (PMID 38896016, 2024). "This review aimed to provide an overall review of how ABCG1 acts in tumor progression." (PMID 38896016, 2024). "Genetic deletion of Abca1 and Abcg1 eliminates tumor-promoting TAMs and slows tumor progression." (PMID 39857239, 2024). "ABCG1 may potentially shift the immunity response to a tumor‐favoring condition through macrophages to promote tumor growth." (PMID 38896016, 2024). "Above all, ABCG1 may function actively in tumor microenvironment especially in macrophages through the regulation of cholesterol hemostasis in cells." (PMID 38896016, 2024). "Thus, inhibition of cholesterol efflux transporters like ABCG1 represents a potential strategy to reprogram TAMs for suppression of tumor growth." (PMID 38896016, 2024). "By acting in TME cells, ABCG1 can have a significant effect on tumor progression." (PMID 39857239, 2024). "According to one study, the lack of ABCG1 prevented tumor growth by causing the macrophages within the tumor to change from tumor-promoting M2 to tumor-fighting M1." (PMID 38540127, 2024). "ABCG1-/- TAMs exhibit intracellular free cholesterol (FC) accumulation and polarization toward the M1 phenotype, activating the IκB kinase/NF-κB pathway, which has a direct killing effect on tumor cells, ultimately inhibiting tumor growth." (PMID 37004014, 2023). "ABCG1 expression is higher in several cancer types compared to normal tissue, expression being associated with higher-grade tumours, metastasis and poor response to chemotherapy." (PMID 36765727, 2023).
tumor (continued). "Moreover, ABCG1 is involved in innate immune response by the regulation of inflammation via reduction of inflammatory cytokines, and in anti-tumor immunity by favoring IL-4–mediated macrophage M2 polarization, producing a pro-cancer effect." (PMID 37108308, 2023). "The targeted silencing of ABCG1 led to EV lipid accumulation and triggered tumor cell death." (PMID 36671802, 2023). "TAMs derived from tumor tissues of Abcg1−/− mice fed with a Western-like diet showed a higher apoptosis rate, shifting from the M2 phenotype to the M1 phenotype with enhanced cytotoxicity for tumor cells and reduced tumor growth." (PMID 34742349, 2021). "Indeed, ABCG1 was expressed at high levels in CRC cells with respect to non-cancerous tissues and to CAFs, and its expression levels in primary tumours are associated with worse prognosis." (PMID 32814794, 2020). "In the present study, we found that AT2 cells with ABCG1 expression were capable of tumor initiation, suggesting that ABCG1 could promote the evolution of AT2 cells into CSCs." (PMID 32157214, 2020). "However, some studies revealed that ABCA1/ABCG1 had different role in tumor progression involving macrophage polarization." (PMID 31598156, 2019). "Our observations also indicate that Abcg1 may be selectively induced in CD8+ T-cells as well as macrophages within the TNBC tumor microenvironment." (PMID 31863071, 2019). "We showed that depletion of ABCG1 reduced HIF-1α around the necrotic area of a tumor." (PMID 30364132, 2018). "We next examined HIF-1α levels in vitro and in vivo and a role of ABCG1 in tumor HIF-1α level." (PMID 30364132, 2018). "The ATP-binding cassette transporter G1 (ABCG1) is a cholesterol lipid efflux pump whose role in tumor growth has been largely unknown." (PMID 30364132, 2018). "ABCG1 was recently shown to influence the anti-tumor function of immune cells." (PMID 29069761, 2017). "We also saw no further inhibition in the rate of tumor development by the additional loss of Abcg1 in myeloid cells (compare DKO to A1−M/−M)." (PMID 29069761, 2017). "Targeting ABCG1 in CSCs could reduce tumor recurrence and improve therapeutic outcomes." (PMID 40370434, 2025). "Additionally, ABCG1 may act as a kinase to phosphorylate downstream molecules and induces tumor growth." (PMID 38896016, 2024). "ABCG1 may confer cancer cell chemoresistance to promote tumor progression." (PMID 38896016, 2024). "Thus, ABCG1 may be another multidrug resistant molecule in tumor through active efflux of antitumor drugs from cancer cells." (PMID 38896016, 2024). "In addition, cholesterol metabolism seems to be an important regulator of macrophage polarization; in the ABCG1 knockdown (transporter for cholesterol efflux) mouse strain, macrophage polarization switched from the tumor-promoting M2 to the anti-tumor-promoting M1 phenotype." (PMID 36077824, 2022). "The same study suggested that ABCG1 could be used as a potential therapeutic target, considering that its depletion leads to the accumulation of extracellular vesicles, which results in tumor regression." (PMID 33805921, 2021). "Furthermore, ABCG1 deficiency in macrophages resulted in changed intrinsic cytokine production, augmented NK cells and CD4+ T cell infiltration in the TME, and prevented tumor growth." (PMID 34742349, 2021). "Therefore in the present study, we have aimed to investigate whether ABCG1-mediated extracellular vesicle (EV) lipid efflux altered tumor growth." (PMID 30364132, 2018). "ATP‐binding cassette subfamily G member 1 is mostly known as a transporter for intracellular cholesterol efflux, and a number of studies indicate that ABCG1 also functions actively in tumor initiation and progression." (PMID 38896016, 2024). "ABCG1 acts as a midstream molecule induced by ECM1α, to promote the phosphorylation of AKT/FAK/paxillin/Rac/Myosin signaling and tumor growth." (PMID 38896016, 2024).